S100A4 (S100 calcium binding protein A4)
Diseases named in the same sentence as S100A4 in open-access papers (continued):
Sharing a sentence is not in itself a finding about the gene and the disease.
asthma (12 papers, 2021 to 2025). "We detected elevated levels of S100A4 in the lung and BALF of OVA-challenged mice, suggesting that S100A4 may be associated with the pathogenesis of asthma." (PMID 37873538, 2023). "In contrast, the mesenchymal markers N-cadherin percent expression, vimentin, and S100A4 positive cell counts generally increased in all pathological groups except in the patients with asthma." (PMID 40475784, 2025). "Until now, S100A4, S100A8/S100A9 (calprotectin), S100A11, and S100A12 have been implicated in the pathophysiology of asthma, exhibiting both similarities and differences in their mechanisms of action." (PMID 41164170, 2025). "Although in the ACO group S100A4 positive basal cells appeared to be higher than the HC (P = 0.3376) and asthma group (P = 0.7417), we noted significantly lower basal cells in ACO than in COPD-ES (P <0.01) and NLFS (P <0.05) groups." (PMID 40475784, 2025). "Experiments involving S100A4−/− mice have shown that those animals displayed less severe asthma signs, further supporting the role of S100A4 in regulating mast cell activation." (PMID 40723867, 2025). "Anti-S100A4 antibody administration alters airway remodeling by preventing EMT in mouse models of asthma." (PMID 37873538, 2023). "The results of this study highlighted the fact that miR‐124‐3p is associated with EMT and asthma progression and functions by suppressing the activation of the TGF‐β1/Smad2 signaling pathway by negatively regulating S100A4." (PMID 36799806, 2023). "To determine this, we used a mouse model of asthma and 16HBE cell line to analyze the effect of S100A4 in asthma." (PMID 37873538, 2023). "Nevertheless, the functions of the miR‐124‐3p/S100A4 axis in the ovalbumin (OVA)‐asthma model are still in their infancy." (PMID 36799806, 2023). "In the asthma mouse model, the expression of S100A4 was also significantly higher in the lung as well as in BALF." (PMID 37026957, 2023). "Second, in this study, we only focused on asthmatic inflammation and EMT, and thus, more experiments are needed to confirm the function of the miR‐124‐3p/S100A4 axis in asthma progression, including fibrosis and oxidative stress." (PMID 36799806, 2023). "Considering that the pathogenesis of this disease has not yet been determined, more studies and experiments are required to identify the upstream and downstream targets of the miR‐124‐3p/S100A4 axis in asthma." (PMID 36799806, 2023). "After establishing asthma models in rodents, we measured the expression levels of miR‐124‐3p and S100A4 and found downregulated expression of miR‐124‐3p and upregulated S100A4 expression." (PMID 36799806, 2023). "Evidence in this study suggests the potential implications of miR‐124‐3p and S100A4 in asthma progression and the potential roles of these two factors in targeted therapy for asthma." (PMID 36799806, 2023). "In the current study, we demonstrate that S100A4 regulated mast cell activation and played a critical role in experimental models of asthma and anaphylaxis." (PMID 34367151, 2021). "S100A4-/- mice exhibited less severe asthma signs which included inflammatory cell infiltration in the lung tissue and BALF, and suppressed mast cell recruitment in the lungs." (PMID 34367151, 2021). "We therefore would like to confirm the effect of S100A4 on this critical mechanism in the current mouse asthma model, which used an independent strain of the S100A4 knockout mice." (PMID 34367151, 2021). "In the present study, we extended this line of research by demonstrating the impact of S100A4 on allergy using a mouse asthma model, and revealing a possible role of S100A4 in mast cell functionality." (PMID 34367151, 2021). "S100A4-positive basal cells in asthma were essentially normal." (PMID 40475784, 2025). "This activation results in the synthesis of eotaxin and further production of S100A4, consequently establishing a positive feedback loop that could perpetuate inflammation in individuals with asthma." (PMID 41164170, 2025).
asthma (continued). "The S100A4 stained RBM cells in asthma remained similar to HC." (PMID 40475784, 2025). "However, further investigations should be conducted to elucidate the mechanisms of S100A4 in asthma." (PMID 37873538, 2023). "However, mice in the asthma mouse model group had moderate expression levels of S100A4 in inflammatory and vascular smooth muscle cells, with prominent S100A4 expression in granulocytes." (PMID 37873538, 2023). "Additionally, increased S100A4 expression has been observed in an allergen‐induced mouse asthma model." (PMID 36799806, 2023). "The treatment effect of S100A4 on OVA-induced asthma was investigated." (PMID 37873538, 2023). "Therefore, in this study, we aimed to explore the possible effects of miR‐124‐3p and S100A4 on inflammation and EMT in asthma using mouse models, and we speculated that miR‐124‐3p might play a role in asthma by regulating S100A4 expression." (PMID 36799806, 2023). "Importantly, stimulation of T cells with S100A4 induces an increase in pro-inflammatory cytokines, particularly eotaxin-2, and they are involved in the pathogenesis of eosinophilic airway inflammation in asthma." (PMID 36386522, 2022). "In general, similar to the epithelial basal cells, both vimentin and S100A4 positive cells in the RBM of pathological groups were elevated except in patients with asthma." (PMID 40475784, 2025). "S100A4, also known as fibroblast-specific protein 1 (FSP1), contributes to asthma by promoting inflammation and epithelial-mesenchymal transition (EMT) in the airway." (PMID 41164170, 2025). "We elucidated the effect of S100A4 on airway remodeling by regulating airway inflammation and epithelial–mesenchymal transition (EMT) in mouse models of asthma." (PMID 37873538, 2023). "However, whether S100A4 mediates the EMT in asthma remains unclear." (PMID 37873538, 2023). "While this specific mechanism has not been investigated in asthma, it is plausible that S100A4 plays a similar role in the airway remodeling observed in asthmatic patients." (PMID 41164170, 2025). "Furthermore, the S100A4-positive basal cells were markedly enhanced in both COPD-ES and CS groups as compared to the HC (P <0.01 and <0.05, respectively) and asthma (P <0.01 and <0.5, respectively)." (PMID 40475784, 2025). "A study focused on S100A4 protein and its connection to airway inflammation, epithelial barrier dysfunction and release of TH2 by VEGFA/VEGFR2 pathway, showing that increased secretion of this alarmin is related to the development of asthma." (PMID 40723867, 2025). "This study also demonstrated a trend of high vimentin and S100A4-positive basal and RBM cells in ACO, and an RBM with the elevated degree of fragmentation as represented by the cleft formation in ACO as compared with HC and asthma." (PMID 40475784, 2025). "Therefore, this study aimed to explore the possible effects of miR‐124‐3p and S100A4 on inflammation and epithelial–mesenchymal transition (EMT) in asthma using mouse models." (PMID 36799806, 2023). "Moreover, the overexpression of miR‐124‐3p or knockdown of S100A4 was found to regulate inflammatory cytokines and EMT, thus attenuating asthma progression, indicating the involvement of miR‐124‐3p and S100A4 in asthma." (PMID 36799806, 2023). "Although the relationship between S100A4 and airway inflammation was elucidated, whether it affects EMT in asthma remains unknown." (PMID 37873538, 2023). "WT and S100A4-/- mice were induced to develop a passive cutaneous anaphylaxis (PCA) model, a passive systemic anaphylaxis (PSA) model, and an ovalbumin (OVA)-mediated mouse asthma model." (PMID 34367151, 2021). "Additionally, intracellular S100A4 blockage attenuated airway remodeling by the inhibition of airway inflammation and EMT process, suggesting that S100A4-antibody therapy may have clinical applicability in controlling airway remodeling in patients with asthma." (PMID 37873538, 2023).
triple-negative breast carcinoma (12 papers, 2015 to 2025). An invasive breast carcinoma which is negative for expression of estrogen receptor (ER), progesterone receptor (PR), and human epidermal growth factor receptor 2 (HER2). "Depletion of Akt3 in triple-negative breast cancer (TNBC) cells increased cell migration and metastases formation in mice by upregulation of S100A4." (PMID 38291468, 2024). "In triple negative breast cancer, LRP6 was able promote tumor migration and invasion by altering the expression and function of S100A4." (PMID 30411539, 2018). "Here, we report that a novel inhibitor of S100A4 can specifically block its increase in cell migration in rat (IC50, 46 μM) and human (56 μM) triple negative breast cancer (TNBC) cells without affecting Western-blotted levels of S100A4." (PMID 37509135, 2023). "In addition, overexpression of the RAGE ligands, S100A7, S100B, S100A4, and S100A8/A9, occurs in both triple-negative breast cancer and colon cancer." (PMID 35727208, 2022). "The study’s aim was to investigate the S100A4-mediated mechanisms of the regulation of tumor cell proliferation and migration in the human triple-positive breast carcinoma cell line MCF-7 (TPBC) and triple-negative breast carcinoma cell line MDA-MB-231 (TNBC)." (PMID 35546077, 2022). "Additionally, when triple-negative breast cancer cells migrate to the brain, astrocytes activate the S100A4-related pathway (protocadherin 7 (PCDH7)-PLCβ-Ca2+-CaMKII/S100A4)." (PMID 33806911, 2021). "Interestingly, several growth factors, such as FGF2, may induce upregulation and release of S100A4 through FGFR1, thus favoring pro-angiogenic and pro-tumoral transduction pathways triggered through the S100A4/RAGE axis in triple-negative breast cancer cells." (PMID 35727208, 2022).
endometrial cancer (11 papers, 2009 to 2025). Primary or metastatic malignant neoplasm involving the endometrium (mucous membrane that lines the endometrial cavity). "We also checked for the expression of genes involved in facilitating metastasis in endometrial cancer, such as S100A4 and TNNT1." (PMID 40433700, 2025). "The role of S100A4 in EMT is supported by RNA interference of S100A4 that suppressed the EMT process in endometrial cancer cells." (PMID 33549040, 2021). "In metastatic breast, ovarian, and endometrial cancer cells, GnRH reduces cell invasion in vitro, metastasis in vivo, and the increased expression of S100A4 and CYR61." (PMID 28824547, 2017). "In line with our findings, DNA hypomethylation and enhanced gene expression of S100A4 can increase invasive ability and promote metastasis in nasopharyngeal, laryngeal, and endometrial carcinoma." (PMID 28498804, 2017). "On the other hand, hypomethylation is also found to be important in regulating the expression of the S100A4 gene in endometrial cancer." (PMID 20814443, 2010). "However, the expression of these metastatic genes, S100A4 and TNNT1, was similar in both type I and type II endometrial cancer." (PMID 40433700, 2025).
psoriasis (11 papers, 2010 to 2026). An autoimmune condition characterized by red, well-delineated plaques with silvery scales that are usually on the extensor surfaces and scalp. "In a xenograft SCID mouse model of human psoriasis, inhibition of S100A4 via a specific blocking antibody led to a significant reduction in epidermal thickness and impairment in cell proliferation." (PMID 36078170, 2022). "S100A4 is involved in the pathogenesis of kidney and pulmonary fibrosis, as well as psoriasis, systemic sclerosis and hypertrophic scarring." (PMID 34830597, 2021). "S100A4 inhibitors significantly reduced epidermal hyperplasia and dermal vascularization and impaired keratinocyte proliferation in an animal model of psoriasis, suggesting that S100A4 positively regulates skin inflammation in psoriasis." (PMID 37891988, 2023). "S100A4 exerts proinflammatory action and has been shown to be involved in the pathogenesis of some chronic immune-mediated inflammatory skin diseases, such as psoriasis and systemic sclerosis." (PMID 34830597, 2021). "Importantly, anti-S100A4 antibodies inhibited the pathological symptoms of psoriasis in a mouse model." (PMID 20442771, 2010). "However, a recent study has demonstrated that a strong up-regulation and release of S100A4 was observed in the upper dermis of psoriatic skin, and blocking antibodies against S100A4 resulted in a significant reduction of psoriatic inflammation in a human psoriasis xenograft SCID mouse model." (PMID 21311769, 2011). "Moreover, our recent data demonstrated strong upregulation of S100A4 in various cell types (e.g. fibroblasts and immune cells), not only in tumor stroma, but also in synovial tissue of rheumatoid arthritis patients and involved skin dermis of patients with psoriasis." (PMID 20442771, 2010).
cardiac hypertrophy (10 papers, 2014 to 2025). "Other studies have shown that S100A4 deficiency improves cardiovascular diseases, including myocardial fibrosis, myocardial hypertrophy, and viral myocarditis 45,46." (PMID 38164183, 2024). "Intriguingly, our finding of decreased systemic S100A4 is in contrast to previous reports, where elevated S100A4 tissue levels were associated with cardiac hypertrophy." (PMID 35053115, 2022). "Furthermore, recently, previous studies by ourselves and other authors have linked S100A4 to several diseases besides cancer, including kidney fibrosis, pulmonary disease, cardiac hypertrophy and fibrosis, arthritis, and neuronal injuries." (PMID 29556233, 2018). "However, the expression of S100A4 is elevated under stress conditions or diseases, including pathological myocardial hypertrophy, myocardial ischemia, and pulmonary hypertension 28,29,45,49." (PMID 38164183, 2024). "S100A4 is also involved in this process as it promotes cardiac hypertrophy in vitro." (PMID 30283351, 2018). "S100A4 has also been reported to be upregulated in cardiac hypertrophy, which is a complex process involved in numerous cellular events, such as cytoskeletal and/or ECM reorganization, energy metabolism, signal transduction, gene expression, and cardiomyocyte apoptosis." (PMID 29204268, 2017). "The promotion of tissue fibrosis by S100A4 has been reported in chronic obstructive pulmonary disease (COPD), pulmonary arterial hypertension (PAH), and cardiac hypertrophy." (PMID 29204268, 2017).
COVID-19 (10 papers, 2021 to 2025). A disease caused by infection with severe acute respiratory syndrome coronavirus 2. "Classical monocytes also transcribed several genes encoding for the S100 protein family, such as S100A4, S100A8, S100A9, and S100A12, which were recently implicated in COVID-19." (PMID 34424199, 2021). "Finally, severe COVID-19 (only in adults) was distinguished by expression of S100 genes, such as S100A4/8/9, and had a more robust inflammatory response as reflected in GOBP enrichment terms, consistent with earlier reports." (PMID 37638019, 2023). "According to some studies, S100A4, S100A9, and S100A10 expression is proportional to neutrophil/lymphocyte ratio, and may reduce peripheral blood lymphocytes in COVID-19 patients." (PMID 35892571, 2022). "In addition, a recent study demonstrated that S100A4, S100A9, and S100A10 have a role in the inflammatory conditions, as well as the severity, of COVID-19 patients, and have the ability to influence the prognosis of the severe form of the disease." (PMID 35892571, 2022).
liver cancer (10 papers, 2017 to 2025). An epithelial or non-epithelial malignant neoplasm that arises from the liver. "Zhu reported that increasing the expression of the S100A4 can lead to the development of liver cancer, which suggests that it could be a potential therapeutic target inducing liver cancer in patients with HBV." (PMID 37628889, 2023). "S100A4 secreted from liver cancer-associated mesenchymal stem cells (LC-MSCs) could promote HCC cell proliferation and invasion, while S100A4 knockdown reduced HCC cell proliferation and invasion." (PMID 29069865, 2017). "On the other hand, CHI3L1 may negatively regulate S100A9 and S100A4, which means that its interaction with S100A9 and S100A4 results in a reduction in the proinflammatory effects of S100A9 and S100A4 in liver cancer." (PMID 38177294, 2024).
metastatic cancer (10 papers, 2014 to 2024). A carcinoma which has spread from the original site of growth to another anatomic site. "The increased protein secretion associated with tumor development and invasiveness has made S100A4 a good biomarker for different metastatic cancers, where it also assumes a prognostic value, since its increase is associated with poor patients survival." (PMID 33918416, 2021). "S100A4 is expressed in most human metastatic cancers and is associated with the premature death of patients with different types of carcinomas, including those from the breast, oral mucosa, bladder, pancreas, prostate, colorectum, oesophagus, lung, stomach, and thyroid glands." (PMID 37509135, 2023). "A member of the S100 family of calcium-binding proteins, fibroblast-specific protein 1 (FSP1), also known as S100A4 and Mts1, is constitutively produced in fibroblasts and metastatic cancer cells." (PMID 38110482, 2023). "The calcium-binding protein S100A4 can induce cell migration/invasion and metastasis in experimental animals and is overexpressed in most human metastatic cancers." (PMID 37509135, 2023). "Accordingly, the inhibition of S100A4 expression in tumor cells suppresses their metastatic potential, and represents a strategy to counteract metastatic cancers." (PMID 33918416, 2021). "Blocking activity of the pro-metastatic S100A4 protein is suggested as a promising approach in the fight against metastatic cancer." (PMID 25884510, 2015). "Notably, S100A4 is overexpressed in metastatic cancers and is characterized as a marker of tumor progression." (PMID 24932473, 2014).
non-small cell lung carcinoma (10 papers, 2002 to 2025). A group of at least three distinct histological types of lung cancer, including non-small cell squamous cell carcinoma, adenocarcinoma, and large cell carcinoma. "However, the association between S100A4 expression and prognosis or clinicopathological parameters in non-small cell lung cancer (NSCLC) remains unclear." (PMID 32696952, 2020). "S100A4 is overexpressed in most cancers, including breast cancer, gastric cancer, and non-small cell lung cancer (NSCLC)." (PMID 30045697, 2018). "The aim of this study was to investigate S100A4-mediated stimulation of ephrin-A1 and osteopontin in non-small cell lung cancer (NSCLC) cell lines, and to characterize the expression of these biomarkers in primary tumor tissue from NSCLC patients." (PMID 22853000, 2012). "S100A4, as a gene related to the regulation of cytoskeleton associated with cell mobility, enhances the non-small cell lung cancer (NSCLC) progression and metastasis, and the detection of S100A4 overexpression could be used to predict a poor NSCLC prognosis." (PMID 29069865, 2017).